STAT1 (signal transducer and activator of transcription 1)
Diseases named in the same sentence as STAT1 in open-access papers (continued):
Sharing a sentence is not in itself a finding about the gene and the disease.
depression (8 papers, 2018 to 2025). "The IRF family and STAT1 are known to play an important role in immune response 75-79 and are associated with anxiety and depression 80-82." (PMID 39310110, 2024). "Moreover, suicidal depressives were found to have increased expression of depression-related interferon-induced genes, presumably regulated by STAT1, compared to healthy individuals." (PMID 40115872, 2025). "Increased prevalence of major depressive disorders has been reported in approximately one-quarter of HCV patients receiving interferon-alpha therapy, which is associated with induced immune activation and increased STAT1 expression and signaling." (PMID 31779701, 2019). "In general, TRD and drug-free patients had similarly increased levels of inflammation-related genes: this applied to both the genes that had been measured before in depression (IL1-beta, IL-6, TNF-alpha and MIF) and those never measured before (A2M, CRP, P2RX7, CCL2 and STAT1)." (PMID 32699209, 2020).
fibrosis (8 papers, 2010 to 2025). the formation of excess fibrous connective tissue in an organ or tissue in a reparative or reactive process. "Our experiment results showed that GGA treatment increased the acetylation of STAT1 and effectively reduced pulmonary inflammation and fibrosis." (PMID 38641226, 2024). "Moreover, Stat1−/− mice had significantly more airway fibrosis as compared to Stat1+/+ mice 21 days after exposure to rMWCNTs." (PMID 28716119, 2017). "We have also reported that V2O5 is a potent activator of type I IFN production by lung fibroblasts that leads to STAT-1 activation and proposed this mechanism in the resolution V2O5-induced fibrosis." (PMID 20175905, 2010).
Hodgkins lymphoma (8 papers, 2015 to 2023). A heterogeneous group of malignant lymphoid neoplasms of B-cell origin characterized histologically by the presence of Hodgkin and Reed-Sternberg (HRS) cells in the vast majority of cases. "Furthermore, Hsp90 inhibitor treatment of classical Hodgkin lymphoma cells was shown to cause inhibition of STAT1, -3, -5, -6 tyrosine phosphorylation probably as a result of decreased expression and phosphorylation of JAK family members." (PMID 29228628, 2017). "In Hodgkin lymphoma cells, inhibition of HSP90 led to loss of JAK1, JAK3, and Tyk2, and constitutive pY of STAT1, 3, 5, and 6 was ablated." (PMID 32272626, 2020). "Interestingly, STAT6 and STAT1 seem to play opposite roles in Hodgkin lymphoma; upon STAT6 knockdown, STAT1 was found to be upregulated in response." (PMID 26073592, 2015). "The Hodgkin lymphoma cell line HDLM-2 has been demonstrated to show constitutive phosphorylation of JAK1 and JAK2, and STAT1, STAT3, STAT5 and STAT6." (PMID 26131691, 2015). "STAT1 (signal transducer and activation of transcription 1) and several STAT1 target genes were included, suggesting that ZHX2 functions as a tumor suppressor in Hodgkin lymphoma." (PMID 36232466, 2022).
Hyperglycemia (8 papers, 2016 to 2022). An increased concentration of glucose in the blood. "HG-increased SOCS-3 expression was associated with STAT1/3, suggesting a possible innovative transcriptional mechanism for hyperglycemia-induced ECM accumulation." (PMID 28129651, 2017). "PARP-1 depletion reversed the hyperglycemia-induced synthetic phenotype switching of VSMCs and macrophage polarization by targeting Stat1." (PMID 31924749, 2020). "Mechanistically, our results suggest that PARP-1 regulates hyperglycemia-accelerated arteriosclerotic calcification by targeting Stat1/Runx2 axis." (PMID 31924749, 2020). "Hyperglycaemia and hyperlipidaemia together contribute to a decline in insulin-producing β-cell mass through activation of the transcription factors nuclear factor kappa-light-chain-enhancer of activated B cells (NF-κB) and signal transducer and activator of transcription (STAT)-1." (PMID 27512950, 2016). "Furthermore, we found that Flu significantly decreased the expression of STAT1 and TGFβ1 in HK-2 cells, which indicates a possible mechanism that DAPA ameliorates EMT by suppressing hyperglycemia-induced STAT1/TGFβ1 pathway." (PMID 31333586, 2019). "Our study revealed that DAPA successfully inhibited hyperglycaemia-induced ECM deposition in the kidneys of diabetic mice, attenuated EMT of tubular epithelial cells under hyperglycemic conditions, and suppressed the level of the profibrotic factors STAT1 and TGFβ1 both in vivo and in vitro." (PMID 31333586, 2019).
malaria (8 papers, 2013 to 2026). Malaria is a serious and sometimes fatal disease caused by a parasite that commonly infects a certain type of mosquito which feeds on humans. "For example, the expression level of STAT1 had an upregulated status among all the malaria groups." (PMID 31614626, 2019). "Furthermore, we showed that SOCS1 expressions were reduced in Stat1−/− cDCs and splenocytes treated with malaria gDNA and RNA, but completely abolished in Stat1−/− cells with IFN-α/β stimulation." (PMID 30470758, 2018). "Across B cell subsets, multiple upregulated Type I IFN signaling response genes were detected, including IFNITM2, ISG20, and STAT1, consistent with the important role of Type I IFN signaling in malaria immune responses across multiple cell subsets." (PMID 37968278, 2023). "Real time PCR was used to quantify the relative expression of STAT-1 and IRF-5, critical transcription factors for M1 polarization, and STAT-6 and c-Maf, salient factors for M2 polarization, in placental macrophages, and compared between malaria positive and negative women." (PMID 40007543, 2025).
myocarditis (8 papers, 2020 to 2025). Myocarditis is a condition that is characterized by inflammation of the heart muscle (myocardium). "This pathogenic cascade is orchestrated by IFN-γ-STAT1 signaling, and therapeutic inhibition of the JAK2/STAT1 axis with ruxolitinib has been shown to reduce cardiovascular mortality in patients with ICI-induced myocarditis." (PMID 40520014, 2025). "Considering IFNγ signaling-recipient cells, decreased motif activity in STAT1 across multiple cell types in myocarditis suggests that the response to IFNγ secreted from cytotoxic NK and CD8 effector cells was downregulated." (PMID 37264110, 2023). "For instance, STAT1 plays a role in regulating the expression of neutrophil gelatinase-associated lipocalin (NGAL) or Lcn2 in influenza-induced myocarditis, leading to neutrophil infiltration caused by myocarditis." (PMID 39769350, 2024). "Our case illustrates that myocarditis could be part of the heterogeneous disease spectrum of STAT1 GOF." (PMID 37020552, 2023). "Consistent with the downregulation of motif activities of IRF3 and IRF7, peripheral immune cells showed a reduced motif activity level of STAT1::STAT2 and IRF9 at the time of myocarditis." (PMID 37264110, 2023). "We describe a STAT1 GOF patient with an incidental finding of elevated cardiac troponins, leading to a diagnosis of a longstanding, slowly progressive idiopathic myocarditis, attributed to STAT1 GOF." (PMID 37020552, 2023). "On the other hand, STAT1, downstream signaling of IFN-γ, exacerbates mouse myocarditis." (PMID 32244307, 2020).
Salmonella Infections (8 papers, 2013 to 2025). Infections with bacteria of the genus SALMONELLA. "This phenotype was associated with an increased STAT1 activation during Salmonella infection." (PMID 34497340, 2022). "SLAMF7 and SLAMF8 signal through NF-κB, IRF7, and STAT-1, and limit mitochondrial ROS accumulation upon Salmonella infection." (PMID 40231463, 2025). "mROS production is triggered by the TLR/TRAF6 pathway in Salmonella infection (or the IFN-γ/STAT1 pathway in Listeria infection), contributing to macrophage clearing of the bacteria." (PMID 35768946, 2022). "Herein, we found a reduced IFN-γ mRNA expression during the establishment of the persistent Salmonella infection and an increased phosphorylation of STAT1 and dephosphorylation of STAT4." (PMID 27472318, 2016). "Salmonella infection induced STAT-1 serine 727 phosphorylation in all the HLA-B27-transfected cells as well as in the mock cells." (PMID 23349666, 2013). "Hence, it has been shown that beside TNF, interferons (IFNs) can trigger epithelial cell death by activating the STAT1 pathway and increased interferon expression was described during Salmonella infection for Casp8ΔIEC mice." (PMID 34497340, 2022). "Collectively, our study reveals that STAT1-signaling is essential to coordinate regulated epithelial cell death and that a disruption of this signaling pathway disturbs mucosal homeostasis during Salmonella infection." (PMID 34497340, 2022). "The majority of these genes were chemokines, cytokines, and other immune related genes with a significant number of genes regulated by Type I and Type II IFN including several members of the Gbp family, Stat1, Usp18 as well as others that are known to be involved in Salmonella infection." (PMID 25161653, 2014). "Since studies suggest that the STAT-1 serine 727 phosphorylation promotes inflammatory responses, our finding provides a mechanism explaining how intracellular Salmonella infection may induce an exaggerated inflammatory response in HLA-B27-expressing cells." (PMID 23349666, 2013). "MSMD (54.0%) accounted for most onset symptoms in patients with STAT1 LOF, whereas 3.0% had Salmonella infection." (PMID 33777053, 2021). "A more plausible explanation is that the altered PKR regulation in HLA-B27 cells modulates the interaction between STAT-1 and PKR leading to a prolonged activation of serine 727 upon Salmonella infection." (PMID 23349666, 2013). "Furthermore, the ratio between STAT1 and STAT4 are crucial for IFN-γ production during viral and Salmonella infections." (PMID 27472318, 2016).
Sjögren’s syndrome (8 papers, 2014 to 2025). "Interferon-γ induces ferroptosis in salivary gland epithelial cells in Sjögren’s syndrome through JAK/STAT1-mediated inhibition of system Xc." (PMID 40934008, 2025). "The effect of polymorphisms in STAT1 and STAT4 associated with Sjögren’s syndrome in cell culture models is currently under investigation in our laboratory." (PMID 38542139, 2024). "Our goal was to investigate the effects of epidermal growth factor (EGF) and interferons (IFNs) on signal transducer and activator of transcription STAT1 and STAT4 mRNA and active phosphorylated protein expression in Sjögren’s syndrome cell culture models." (PMID 38542139, 2024). "Finally, we examined this IRG signature (ISG15, SIGLEC1, STAT1 RSAD2, IFI27 and IFI44L) in peripheral blood mononuclear cells (PBMCs) collected from a smaller cohort of healthy controls, disease controls, AAV and primary Sjogren’s syndrome (pSS) patients." (PMID 33859290, 2021). "Not much is known about NK cells in Sjögren's syndrome, so the correlation with basal phosphorylation of ERK, STAT1 Y701, and STAT3 Y705 in NK cells is especially interesting." (PMID 30846988, 2019).
Allergy (7 papers, 2012 to 2025). An allergy is an immune response or reaction to substances that are usually not harmful. "STAT1 activation has been implicated in the pathogenesis of allergic diseases." (PMID 40650018, 2025). "STAT1, STAT3, TLR8, IL13, RFX5 gene polymorphisms have been demonstrated as susceptibility loci for the immune dysregulation in various inflammatory and allergic diseases." (PMID 32886659, 2020). "Therefore, the most promising protein combination as allergy triggers would be formed by AKT1, MAPK13, and STAT1 proteins." (PMID 33936056, 2021). "In addition, repression of STAT1 decreased the effects of downstream STAT1-dependent inflammatory mediators, including secondary effects on inflammatory cells, including Th cell cytokine and chemokine production, Ag-specific Ig levels, and mucous cell metaplasia in OVA induced allergy model." (PMID 36980282, 2023).
B-cell lymphoma (7 papers, 2015 to 2025). "We repeated NK-92 competitive co-culture experiments after disruption of DCAF15, PTPN2, STAT1 and ICAM1 in Daudi cells, a B2M-deficient B-cell lymphoma line." (PMID 31452512, 2019). "Moreover, it has been described to repress the anti-proliferative and pro-apoptotic IFN/STAT1 axis in B-cell lymphoma." (PMID 27791205, 2016). "In addition, inhibition of JAK2 does not only block the activation of STAT3 but also the activity of STAT1 in B-cell lymphoma." (PMID 26654227, 2015). "STAT3 inhibition also synergized with inducers of type I IFN, a downstream effector of the cGAS-STING pathway, to effectively inhibit B cell lymphoma growth, possibly by alleviating the suppressive effects of STAT3 on IRF7, IRF9, STAT1, and STAT2 expression." (PMID 40743845, 2025).
cardiac hypertrophy (7 papers, 2020 to 2025). "Our data also showed that TNIP3 increased protein level of STAT1 in cardiac hypertrophy and even in hypertrophic cardiomyocytes under cycloheximide treatment." (PMID 38926347, 2024). "To illustrate the mechanism of how TNIP3 regulates pathological cardiac hypertrophy, we combined RNA-Seq and mass spectrometry data to analyze and identify STAT1 to serve as the potential target of TNIP3." (PMID 38926347, 2024). "Remarkably, preservation effect of TNIP3 on cardiac hypertrophy was blocked by STAT1 inhibitor Fludaradbine or STAT1 knockdown." (PMID 38926347, 2024). "Mechanistically, RNA-sequencing and interactome analysis were combined to identify the signal transducer and activator of transcription 1 (STAT1) as a potential target to clarify the molecular mechanism of TNIP3 in pathological cardiac hypertrophy." (PMID 38926347, 2024). "It plays a critical role in the normal development of cardiovascular systems and participates in the pathogenesis of cardiac hypertrophy through activation of JAK/STAT1/3, Ras/ERK1/2, and PI3K/AKT signaling pathways." (PMID 36195937, 2022). "The STAT1 S727A modification additionally caused a significant reduction in plaque content of macrophages and CD3 T cells and diet‐induced cardiac hypertrophy index." (PMID 34569651, 2021). "Future studies should therefore investigate the effect of STAT1 S727A modification on cardiac hypertrophy induced by sustained pressure overload." (PMID 34569651, 2021). "Both IFN‐γ and STAT1 have been found to protect against pressure overload‐induced cardiac hypertrophy." (PMID 34569651, 2021). "Collectively, these data indicated that the reduction of STAT1 could abolish the protective effect of TNIP3 against cardiac hypertrophy." (PMID 38926347, 2024). "In addition, as STAT1 has been previously shown to cause loss of cardiac myocytes by promoting apoptosis and also reducing cardioprotective autophagy, the role of STAT1 S727 phosphorylation in these and other processes that contribute to cardiac hypertrophy needs to be investigated." (PMID 34569651, 2021). "Considering the promotive effect of TNIP3 on total STAT1 protein during cardiac hypertrophy, we further investigated whether TNIP3 could affect the degradation of STAT1." (PMID 38926347, 2024).
coccidioidomycosis (7 papers, 2016 to 2025). A fungal infection caused by Coccidioides immitis. "Autosomal dominant STAT1 deficiency is a monogenic defect that increases susceptibility to coccidioidomycosis in humans." (PMID 41607488, 2025). "In this study, we identified the first case of disseminated coccidioidomycosis in a patient with AD STAT1 deficiency." (PMID 41607488, 2025). "Here, we present the first case of disseminated coccidioidomycosis in a patient with AD STAT1 deficiency." (PMID 41607488, 2025). "In humans, polymorphisms in the IL-12/IFN-γ signaling pathway result in STAT1 gain-of-function mutations that are associated with increased disease severity in Coccidioides infection." (PMID 38250880, 2024). "STAT1 GOF mutations not only cause infection but also cause other non-infectious symptoms, such as deep fungal diseases such as coccidioidomycosis and histoplasmosis, an increased susceptibility to bacterial sinus and lung infections, mycobacteria infection, and herpes virus infection." (PMID 36225936, 2022).
hearing loss (7 papers, 2017 to 2023). "We report two novel likely pathogenic variants in SGPL1 and STAT1 that, in combination, led to increased propensity for opportunistic infections in a patient with additional features of hearing loss, nephrotic syndrome and ichthyosis." (PMID 37377976, 2023). "At the end point of our study at 8 w.p.i. the auditory function in our LASV-infected Stat1-KO mice were still in a trend of progressively declining, which suggests a different hearing loss etiology." (PMID 35605008, 2022). "In this study, we report that STAT1-KO mice presented hearing impairment and loss of function of STAT1 resulted in inflammatory processes within the middle ear." (PMID 32991625, 2020). "In this study, we focused on STAT1 as a target for new drug development against cisplatin-induced hearing loss." (PMID 28703809, 2017). "Additionally, the STAT1-/- model is useful as a new platform for investigating the mechanism of LF-associated hearing loss, which affects approximately one third of survivors." (PMID 32155851, 2020). "The STAT1-/- mouse model is the only known animal model for studying LASV-associated hearing loss." (PMID 32155851, 2020). "The levels of the transcription factors, STAT1 and STAT3 (which are associated with cisplatin-induced hearing loss) showed differential regulation, with the levels of STAT1 showing peak increases in 12 h, which diminished over 72 h." (PMID 37063917, 2023). "We found ABR responses were affected in STAT1-KO mice with cases of bilateral and unilateral hearing impairment." (PMID 32991625, 2020). "All STAT1-KO animals of 12–13 weeks presented hearing impairment suggesting a 100% incidence, while STAT1-KO mice of 9 and 18 weeks showed hearing impairment in 3 out of 8 and 7 out 13, respectively, suggesting a moderate incidence ranging from 37.5–54%." (PMID 32991625, 2020). "STAT1-KO mice of 9 and 13 weeks with unilateral or bilateral hearing impairment presented from moderate to high levels of inflammation in the affected ear." (PMID 32991625, 2020).
Listeria monocytogenes infection (7 papers, 2010 to 2022). "Mice with macrophage-specific deletion of STAT1 are susceptible to listeriosis." (PMID 26834734, 2015). "In listeriosis, type I IFNs, which also activate STAT1, are mainly produced by macrophages and exacerbate the diseases." (PMID 26834734, 2015). "Related to these findings, cell type-restricted deletion of Stat1 in MØ, monocytes, and granulocytes (LysM Cre+Stat1f/f) but not DCs (CD11c Cre+Stat1f/f) resulted in enhanced lethality after Listeria monocytogenes infection." (PMID 24743949, 2014). "Blockage of STAT1 Ser phosphorylation, using STAT1 Ser mutants, significantly altered the IFNγ transcriptional response and its ability to clear Listeria monocytogenes infection, highlighting the relevance of STAT1 Ser phosphorylation in modulating IFNγ response in macrophages." (PMID 33357429, 2020). "Interestingly, the IRF9, STAT1, STA3, and NF-κB can bind to promoter region of Nos2 gene and induce its transcription during Listeria monocytogenes infection, suggesting both direct and indirect routes for miR-302d regulation of Nos2 expression." (PMID 30949455, 2019). "STAT1, after activation by IFN-γ signaling, leads to the activation of peritoneal macrophages, resulting in enhanced bacteria killing and protection against lethal levels of Listeria monocytogenes infection in mice." (PMID 20858287, 2010).